ABCG2 (ATP binding cassette subfamily G member 2 (JR blood group))
Diseases named in the same sentence as ABCG2 in open-access papers (continued):
Sharing a sentence is not in itself a finding about the gene and the disease.
breast cancer (continued). "Thus, in the final experimental set, we monitored the effect of talazoparib on the expressions of ABCB1, ABCC1, and ABCG2 in breast cancer MCF-7 cells." (PMID 36430819, 2022). "Both ABCC1 and ABCG2 were reported to mediate estradiol-induced S1P release in breast cancer cells." (PMID 35565311, 2022). "It was shown that an increased miR-200c level might cause an indirect transcriptional regulation of ABCG2 by targeting transcription factors such as BMI-1 in melanoma cells and ZEB1 in human breast cancer cells." (PMID 33806009, 2021). "Studies of the breast cancer drug resistance mechanism revealed that ABCG2 could pump chemotherapeutic drugs out of tumor cells, and estradiol enhanced this pumping effect." (PMID 34144706, 2021). "In addition, miRNA-298 effectively targeted ABCC1, enhancing the sensitivity to DOX, whereas miRNA-328 and miRNA-487a amplified breast cancer cells’ sensitivity to mitoxantrone (MX) by directly targeting ABCG2." (PMID 34771496, 2021). "ABCG2 or BCRP or Breast Cancer Resistance Protein (encoded by the ABCG2 gene) was originally isolated from P-gp-negative multidrug-resistance breast cancer cell lines." (PMID 33946618, 2021). "Even though ABCG2 is reported to be active in embryonic stem cells and other Quiescent stem cells, it is enriched more in the Progenitor-like population than in the Quiescent population, when analyzed by single-cell RNA-Seq in CSCs of breast cancer." (PMID 34150761, 2021). "As a dual kinase inhibitor of human epidermal growth receptors EGFR and HER2 for breast cancer treatment, lapatinib is a substrate for ABCG2 and P-glycoprotein (P-gp), another ATP-binding cassette family protein commonly involved in multidrug resistance to cancer chemotherapy." (PMID 34545713, 2021). "Similarly, the expression level of miR-328-3p was low in breast cancer, but the ATP-binding cassette sub-family G member 2 (ABCG2) level was high." (PMID 32792861, 2020). "ABCG2 is related to breast cancer cell resistance to doxorubicin when overexpressed." (PMID 33316872, 2020). "By DNA methylation analysis of the ABCB1, ABCC1, and ABCG2 promoters in three breast cancer cell lines (MCF7, luminal A subtype; ZR-75-1, luminal B subtype; MDA-MB-231, triple negative subtype), the ABCC1 promoter has been found to be unmethylated in each of the cell lines." (PMID 33066132, 2020). "ABCG2 transports several drugs used for breast cancer treatment." (PMID 33334016, 2020). "At the same time, reactive oxygen (ROS) generated from intracellularly delivered Ce6 by laser irradiation arrested the activity of ABCG2 efflux receptor overexpressed in doxorubicin-resistant breast cancer cells (MCF-7/ADR), resulting in increased the chemotherapy efficacy." (PMID 32897469, 2020). "In addition, our results indicate that the overexpression of H19 and miR-675 observed in cancer cells is accompanied overall with an overexpression of different stem cell markers such as Sox2, Oct3/4 and Abcg2 in breast cancer cell lines." (PMID 32610610, 2020). "Similarly, in oral cancer and triple negative or ER+ breast cancer cells, the AHR was shown to regulate aldehyde dehydrogenase (ALDH), which, like ABCG2, is associated with chemotherapy export." (PMID 33396563, 2020). "Chrysin may also regulate ABCG2 mediated nitrofurantoin transport on ABCG2-overexpressing human MCF-7 breast cancer cells by increasing the area under the curve (AUC)." (PMID 31245292, 2019). "A number of microRNAs demonstrated inhibitory effects on ABCG2 expression in breast cancer cells." (PMID 31443516, 2019). "Besides breast cancer, ABCG2 overexpression was also found in many other cancer types including lung cancer and leukemia." (PMID 34322663, 2019). "Further, ABCG2 knockdown in primary breast cancer and BT-20 cells increased the chemosensitivity." (PMID 30617282, 2019).
breast cancer (continued). "In conclusion, direct exposure to 5‐ALA and the ABCG2 inhibitor Ko143 may be the first step toward realizing the utility of fluorescence‐based breast cancer detection by FNA." (PMID 31385432, 2019). "In addition, inhibition of GHR signaling sensitized breast cancer cells to chemotherapy by decreasing ABCG2, which resulted in lowering the drug effluxing capabilities of ER−ve breast cancer cells." (PMID 30617282, 2019). "MRP8 is encoded by ARCC11 genes and pumps 5-fluorouracil whereas MXR/BCRP (multixenobiotic resistance and breast cancer resistance proteins, respectively) encoded by ABCG2 genes causes mitoxantrone, topotecan, doxorubicin, daunorubicin, CPT-11, imatinib, and methotrexate resistance." (PMID 31159219, 2019). "Moreover, we highlight the functional role NRP-1 plays in breast cancer resistance by attenuating ABCG2." (PMID 29728077, 2018). "Multidrug resistant (MDR) proteins, ABCB1 and ABCG2 are breast cancer resistance genes." (PMID 29187162, 2017). "This affected ABCG2′s cellular localization and drug transporter function in breast cancer cells." (PMID 28445958, 2017). "Nonetheless, research on the correlation of ABCG2 gene polymorphism and breast cancer susceptibility is lacking, which this study attempts to address in a Chinese Han population." (PMID 29340035, 2017). "Besides MDR1 the best known are multidrug resistance related protein (MRP1, ABCC1) and breast cancer related protein (BCRP, ABCG2)." (PMID 28056859, 2017). "In addition, ABCG2 alone can be considered a suitable marker for breast cancer, in particular for TNBC phenotype." (PMID 28760736, 2017). "In conclusion, this study found that ABCB1 C3435T and ABCG2 C421A genotypes were not significantly correlation with the susceptibility to breast carcinoma in a Chinese Han population." (PMID 29340035, 2017). "Treatment with terrein significantly suppressed growth of ABCG2-expressing breast cancer cells." (PMID 28330151, 2016). "In conclusion, this study suggests that knockdown of SALL4 inhibits the proliferation of MCF-7/ADR cells through arresting the cell cycle in the G1 phase and that down-regulation of SALL4 reverses the drug resistance of breast cancer by reducing the expression of ABCG2 and c-myc." (PMID 26935744, 2016). "In addition, miR-181a and miR-487a can sensitize mitoxantone-resistant breast cancer cells to chemotherapeutic agents by targeting ABCG2." (PMID 27834829, 2016). "Moreover, analysis of the data from TCGA database revealed that MRP1 expression level in breast cancer samples was higher than that of most other ABC transporters, such as ABCB1 and ABCG2, which are reported to be associated with drug resistance." (PMID 27487127, 2016). "We determined the methylation patterns in tumor, tumor-adjacent and tumor-distant tissues from the same breast cancer patients in order to investigate if aberrant promoter methylation levels of ABCB1, ABCC1 and ABCG2 can be used as indicator for detection of field cancerization in breast cancer." (PMID 27689338, 2016). "In addition, we investigated if aberrant promoter methylation levels of ABCB1, ABCC1 and ABCG2 occur in tumor and tumor-surrounding tissues from breast cancer patients." (PMID 27689338, 2016). "Similarly, miR-487a regulates the chemosensitivity of breast cancer cells to mitoxantrone via direct targeting of ABCG2." (PMID 25860815, 2015). "One possible explanation for these findings may be the level of ABCG2 expression, a known and effective resistance mechanism of mammary tumors enabling them to evade topotecan-induced DNA damage." (PMID 26623560, 2015). "Immunohistochemical studies involving breast cancer clinical samples also associated high levels of HIF-2α to tumor size, lymph node metastases, distant metastasis, and poor prognosis in patients with breast cancer, and to histology grade, Ki67 and ABCG2 expression." (PMID 26305551, 2015).
breast cancer (continued). "Although elevated expression of ABCG2 or ENPP1 was not correlated with recurrence of breast cancer, co-expression of ABCG2 and ENPP1 was moderately associated with poor prognosis (HR=1.84; P=0.062)." (PMID 26065921, 2015). "This study tested the hypothesis that COX-2 inhibitor celecoxib plays a role in regulating ABCG2 expression in human breast cancer cells." (PMID 25587329, 2014). "To clarify whether ABCG2 inhibition is involved in the sensitizing effect of celecoxib, we investigated whether the expression of ABCG2 in breast cancer cell lines, could be modulated by celecoxib." (PMID 25587329, 2014). "In order to verify whether the observed effects at mRNA level were mirrored by parallel changes in ABCG2 protein levels, flow cyotmtry analysis for ABCG2 was performed using breast cancer cells treated for 4 and 24 h with TPA 10 nM and celecoxib 40 μM." (PMID 25587329, 2014). "ABCG2 was initially isolated from a doxorubicin-resistant MCF-7/AdrVP breast cancer cell line." (PMID 24179544, 2013). "HIF-2a could regulate ABCG2 in breast cancer cells, and could be a novel potential bio-marker to predict chemotherapy effectiveness." (PMID 22452996, 2012). "Recently we identified a novel mechanism of MDR in which ABCG2-rich extracellular vesicles (EVs) form in between attached neighbor breast cancer cells and highly concentrate various chemotherapeutics in an ABCG2-dependent manner, thereby sequestering them away from their intracellular targets." (PMID 22530032, 2012). "Thus, we next explored the possible formation of EVs in additional human malignant tumor cell lines including gastric carcinoma N-87 cells that lack ABCG2 expression and flavopiridol-resistant breast cancer MCF-7/FLV1000 cells with ABCG2 overexpression." (PMID 21283667, 2011). "The data about the contribution of ABCG2 to drug resistance in breast cancer are scarce." (PMID 21943250, 2011). "Therefore, further studies are needed to explore the expression of ABCG2 in primary breast cancer and its correlation with the clinicopathological and biological characteristics of the breast cancer." (PMID 21943250, 2011). "Furthermore, the expression of ABCG2 is correlated with the expression of HER2 significantly (p = 0.001) by means of statistic analysis of 196 breast cancer cases detected by IHC." (PMID 21943250, 2011). "Importantly, miR-520g is computationally predicted to target a number of breast-cancer-related genes including ABCG2 (BCRP)." (PMID 19432961, 2009). "Notably, ABCG2 has emerged as a predominant factor in chemoresistance, especially in breast cancer." (PMID 41541684, 2026). "Of note, TNBCs are more likely to overexpress multi-drug-resistant protein-1 (ABCC1/MRP1), multi-drug-resistant protein–8 (ABCC11/MRP8), and the breast cancer resistance protein (ABCG2/BCRP) compared to other breast cancer subtypes, which may contribute to poor response to chemotherapy." (PMID 40420099, 2025). "Also, it was suggested that miR‐519c would affect ABCG2 expression in MCF‐7 human breast cancer cells, and the presence of miR‐519c target site on ABCG2 3′UTR may control the ABCG2 mRNA expression by getting involved in mRNA cleavage mechanism." (PMID 37166017, 2023). "Additionally, using in vivo models, downregulation of CAV1 in breast-cancer stem cells also effectively impaired the tumorigenicity and chemoresistance, highlighting the importance of the CAV1-regulated β-catenin/ABCG2 signaling axis in chemoresistance of breast-cancer stem cells." (PMID 35158857, 2022).
breast cancer (continued). "Thus, the post-hypoxia/oxidative stress [SPm (hox)+/ABCG2+ CSCs of several cell lines that we previously characterized for the TS phenotype SPm (hox) enriched in EpCAM+/ABCG2+ CSCs], including oral cancer, breast cancer, and lung cancer, were infected with Mtb-m18b and BCG." (PMID 36248858, 2022). "In addition, multiple ABC transporters including ABCG2 enhance drug resistance in breast cancer." (PMID 35768871, 2022). "Among the delivered proteins are frequently described ATP-binding cassette (ABC) family, like P-glycoprotein (P-gp, MDR1, and ABCB1), breast cancer (BC)-resistant proteins (ABCG2, BRCP, and ABCA3), and multidrug-resistant protein 1 (MRP-1)." (PMID 36091133, 2022). "Similar differences were observed for the breast cancer risk gene ABCC11 (1.8 in East Asians compared to 0.5 in Africans), as well as the multi-drug resistance genes ABCB1 (1.4 in South Asians compared to 0.2 in Africans) and ABCG2 (1.3 in East Asians compared to 0.1 in Europeans)." (PMID 32206879, 2020). "However, TPS-A has also been shown to inhibit tubulin polymerization and breast cancer resistance protein (BCRP, ABCG2), and an effective inhibition of BCRP by TPS-A has been shown to restore the efficacy of clinically used chemotherapeutics when tested on BCRP+ breast cancer cell lines." (PMID 33643664, 2020). "It has been observed that blocking ABCB1 or ABCG2 with the specific exogenous siRNAs can reverse multidrug resistance in diverse cancer cells; even more, the concomitant application of both siRNAs using a nanoparticle-facilitated delivery showed a synergic effect in breast cancer cells." (PMID 31878061, 2019). "Furthermore, ABC transporters such as multidrug-resistance-associated protein 1 (MRP1), multidrug-resistance protein 1 (MDR1), and ATP-binding cassette super-family G member 2 (ABCG2) are overexpressed in the CSCs of breast cancer, pumping out chemicals such as anti-cancer drugs or Hoechst 33342." (PMID 30875792, 2019). "Therefore, knocking down ABCG2 gene expression might effectively reverse drug resistance in breast cancer cells." (PMID 26575421, 2015). "The hypoxia/HIF-2a/ABCG2 pathway could be a new mechanism of breast cancer multidrug-resistance." (PMID 22452996, 2012). "ABCG2-mediated multidrug resistance (MDR) is a major challenge among chemotherapeutic treatments of colon, pancreatic, and breast cancer, as well as leukemia." (PMID 41678660, 2026). "By enhancing the bioavailability and stability of ABCG2 inhibitors, this research contributes to the ongoing efforts to develop more effective strategies for combating MDR in breast cancer and other chemoresistant malignancies." (PMID 41471102, 2025). "ABCG2, also known as breast cancer resistance protein (BCRP), was isolated as a gene highly expressed in resistant breast cancer cells." (PMID 40362545, 2025). "Salinomycin also can remove markers on the surface of breast cancer cells by inhibiting Wnt signaling transduction, such as CD44 and ABCG2, a drug resistance marker." (PMID 41211430, 2025). "Knockout of Fzd2 significantly reduced the expression of ABC transporter subfamily G isoform 2 (ABCG2) and IC50 of paclitaxel, indicating that knockout of Fzd2 enhanced the sensitivity of breast cancer cells to paclitaxel." (PMID 41211430, 2025). "The upregulated differentially expressed breast cancer stem cell markers included CD56/NCAM1, POU5F1, PROCR/CD201, ITGA6, and the downregulated were ESR1, PGR, HER2/ERBB2, ABCG2, CD44, CD24, EPCAM, and CDH1." (PMID 40690373, 2025). "A quantitative proteomic study of human brain metastases from lung and breast cancer patients found that P-gp/ABCB1 and BCRP/ABCG2 were undetectable in the microvessels of over 80% of samples when compared to the noncancerous cerebral cortex." (PMID 40806198, 2025).
breast cancer (continued). "In this study, the effects of these inhibitors on the expression levels of PD-1, PD-L1, and drug resistance-related proteins, including ABCG2, MDR-1, and MRP-1, were evaluated across breast cancer cell lines within distinct immune microenvironment contexts." (PMID 40725123, 2025). "For breast cancer, miR-483-3p and miR-138-5p showed favorable predictions against ABCB1/PTP4A2 and TMBIM6, respectively, while miR-365 and miR-331-3p mapped to ABCG2/AP2M1." (PMID 41378310, 2025). "Moreover, recent clinical investigations have demonstrated that both ABCG2 expression levels and genotypic variants are predictive of disease progression and treatment response in breast carcinoma, glioma, hepatoma, lymphoma, nonpapillary renal cell carcinoma, and Non-Small Cell Lung Cancer." (PMID 40806557, 2025). "Like ABCG2, SLC1A5 is overexpressed in many human tumors including breast cancers, and its overexpression has been correlated with poor prognosis." (PMID 38641063, 2024). "In the mitoxantrone-resistant breast cancer cell line MCF-7/MX100 overexpressing ABCG2 transporter, miR-328 was able to increase the sensitivity to mitoxantrone by decreasing the ABCG2 protein expression via complementary targeting the 3′UTR of ABCG2 mRNA." (PMID 39114355, 2024). "Ribociclib, a CDK4/6 inhibitor approved for the treatment of locally advanced/ metastatic breast cancer, revealed ABCB1 and ABCG2-mediated daunorubicin and mitoxantrone efflux inhibition in AML cell lines and in CD4+/Flt3-WT leukemia cells." (PMID 38255216, 2024). "The differential expression of ABCG2 and ALDH1 markers between HCT-116 cells and MDA-MB-231 breast cancer cells indicates different characteristics and behavior of these cell lines." (PMID 38787133, 2024). "ABCG2 for example is known as the human breast cancer-resistance protein (BCRP) and is a marker of resistance to breast cancer chemotherapy." (PMID 39857239, 2024). "miR-328 regulates the expression of the ABCG2 protein by targeting its ABCG2 3’-UTR, thereby influencing drug disposition in human breast cancer cells." (PMID 38807590, 2024). "Nearly 80% of the SKBR3 breast cancer cells were highly positive for the expression of both drug transporter proteins ABCG2/CD338 and MDR1/CD243, while 10% of the MCF7 cells expressed CD338/ABCG2." (PMID 36834918, 2023). "ABCG2 (breast cancer resistance protein, BCRP) is the major drug efflux transporter in breast cancer." (PMID 37569629, 2023). "In the present study, we used bioinformatics and experimental analysis to investigate the role of miR‐548 K, in the modulating of ABCG2, in MDR breast cancer cells." (PMID 37166017, 2023). "Various molecular processes are involved in the development of MDR in breast cancer cells, including over expression of ABC transporters such as ABCG2 (BCRP), increase breast cancer stem cells drug resistance, and epithelial mesenchymal transition." (PMID 37166017, 2023). "As an in vitro model of chemoresistance, we used colon and breast carcinoma cell lines, and the MCF-7 Doxo cell line, in which the ABCG2 expression was proven to be upregulated, as further reported by several independent studies." (PMID 38004447, 2023). "No influence in anthracycline pharmacokinetics was reported with ABCG2 in an AML cohort with daunorubicin (rs2231137, rs2231142, rs769188) or a breast cancer cohort with doxorubicin (rs2231142)." (PMID 35456712, 2022). "There is a close relationship between the overexpression of ABCG2 and the development of MDR in lung, colon, and breast cancer." (PMID 34830383, 2021). "While these CD44high clusters showed a downregulation in stem cell markers ALDH1A1 and ABCG2, they did show an increase in ALDH2, a stem cell marker less common in breast cancer." (PMID 34579762, 2021). "As an FDA-approved kinase inhibitor for breast cancer treatment, lapatinib is ready to be used in combination with ALA for therapeutic enhancement in tumors with elevated ABCG2 activity." (PMID 34545713, 2021).